FLT4 (fms related receptor tyrosine kinase 4)
Diseases named in the same sentence as FLT4 in open-access papers (continued):
Sharing a sentence is not in itself a finding about the gene and the disease.
peripheral vascular disease (2 papers, 2019 to 2020). Any disorder affecting blood flow through the veins or arteries outside of the heart. "Interestingly, a similar decrease in the expression of VEGFR-3/Flt-4 that likely contributes to a defective lymphangiogenic/lymphvasculogenic function has previously been reported in circulating lymphatic endothelial progenitor cells from SSc patients with severe peripheral vascular disease." (PMID 31817940, 2019).
pulmonary atresia (2 papers, 2022 to 2024). "In the present study, both patients of Family I had the identified FLT4 variant, which is associated with large ventricular septal defects and pulmonary atresia with hypoplastic pulmonary artery branches and multiple aortopulmonary collaterals." (PMID 36496429, 2022).
acute lymphoid leukemia (1 paper, 2025). "An understudied phenomenon is the overexpression of the RTK FLT4 and its specific ligand VEGFC, as well as its association with treatment failure, in pediatric acute lymphoid leukemia." (PMID 40316529, 2025).
chronic heart failure (1 paper, 2020). "In addition, human heart samples were obtained from healthy donors or patients with chronic heart failure, and the gene expression of lymphatic endothelial markers VEGFC, LYVE1, PDPN, and FLT4 was assessed." (PMID 33200983, 2020).
Cognitive impairment (1 paper, 2021). Abnormal cognition is characterized by deficits in thinking, reasoning, or remembering. "At the same time, a higher expression of VEGFB, FLT4, FLT1, and PGF in the prefrontal cortex was related to the stronger cognitive impairments in patients indicating impaired neural network function." (PMID 33672819, 2021).
DOCK8 immunodeficiency syndrome (1 paper, 2023). "These genes are linked with a range of X-linked and autosomal disorders, e.g., TMLHE (X-linked Autism), CDKL5 (Developmental Encephalopathy), FANCD2 (Fanconi anaemia), FLT4 (congenital heart defects), FTCD (Glutamate formiminotransferase deficiency), and DOCK8 (DOCK8 immunodeficiency syndrome)." (PMID 38033082, 2023).
malaria (1 paper, 2021). Malaria is a serious and sometimes fatal disease caused by a parasite that commonly infects a certain type of mosquito which feeds on humans. "Genes with top scores encode for different malaria relevant functions such as regulation of inflammation (CSMD1), neural adhesion (CNTN4, PCSK5, CDH13, TMEM132), vascular epithelial development (FLT4), and protein kinases (PTPRT, PRKG1)." (PMID 34868193, 2021).
oral cancer (1 paper, 2023). "At present, there are few studies on the influence and correlation of FLT4 on oral cancer cells." (PMID 38050610, 2023). "Therefore, in the later stage, we plan to observe whether the physiological function of cancer cells changes and the changes of its related pathways by knocking down the expression of FLT4 in oral cancer cells." (PMID 38050610, 2023).
schizophrenia (1 paper, 2020). A major psychotic disorder characterized by abnormalities in the perception or expression of reality. "Burden significance for both FLT4 and NOTCH1 was highly specific to CHD compared to an unrelated schizophrenia sample and was further confirmed by the gnomAD singleton comparison analysis." (PMID 33110418, 2020).
Stillbirth (1 paper, 2023). Death of the fetus in utero after at least 22 weeks of gestation. "The Fms-related receptor tyrosine kinase 4 (FLT4) was associated with 18 bovine traits including length of productive life, somatic cell score, fertility (calving ease, stillbirth), and udder traits." (PMID 37512987, 2023).
thymic tumor (1 paper, 2015). "We aimed to analyze genotypes of VEGF-A, VEGFR2, Flt4, PDGFRα, HIF-1α and ERCC1 and their correlation with thymic tumor risk and patient outcome." (PMID 26254278, 2015).
tongue tumors (1 paper, 2012). "In both primary tongue tumors and tumor-bearing SLNs, lymphatic vessels close to tumor cells expressed Flt-4." (PMID 23031500, 2012).
tumor (524 papers, 1999 to 2026). "Based on these results, expression levels of BIRC5, HIF1A, and FLT4 associated with primary NSCLC tumor progression and metastasis were compared to normal samples." (PMID 37509650, 2023). "The mutations were detected both in tumor tissue and CSF samples, apart from FLT4 and CIC mutations." (PMID 37822669, 2023). "HNF1A, ESR1, and FLT4 were mutated significantly more frequently in tumor tissue samples obtained from patients with stage III BC, while SYNE1, PER1, and LRP1B were mutated significantly more frequently in stage IV BC." (PMID 32731384, 2020). "The VEGFC-mediated lymphangiogenesis is suggested to be maintained via a paracrine mechanism in which the Flt4 expressed on the lymphatic endothelial cells is activated via its association with tumor cell-derived VEGFC." (PMID 32752094, 2020). "The FLT4 gene was altered in 1 tumor (1.1%), showing one already known missense mutation in the immunoglobulin I-set domain." (PMID 31548566, 2019). "We found limited genetic concordance between primary and secondary tumor sites with private mutations in FLT4, MTOR, ITGA5, SETD2, PBRM1, and BRCA1 on progression." (PMID 29088767, 2017). "Vascular endothelial growth factors (VEGF) -C and -D and their corresponding receptor (VEGFR3/Flt4) are the main actors in the development of tumour-associated lymphatic vessels." (PMID 28771186, 2017). "These associations confirm the role of VEGFR3/FLT4/CD310 in tumor progression and dissemination." (PMID 41459512, 2025). "Interestingly, an increase in Flt-4-positive LN sinuses was observed in all tumor-associated LNs." (PMID 23031500, 2012). "Overall, these xenograft model results indicate that FLT4 accelerated tumor cell proliferation primarily in females." (PMID 40316529, 2025). "VEGFR3/FLT4/CD310 receptor is known to be expressed in stromal cells that contribute to tumor growth and survival, and the use of VEGFR3 inhibitors affects tumor infiltrate." (PMID 41459512, 2025). "Various tumor antigens—including VEGFR2, EGFR, HER2, MAGE, MUC1, FGFR, Flt4, and tumor-associated carbohydrate antigens—have been used in preclinical vaccine candidates." (PMID 40427029, 2025). "Overall, our findings offer new insights into the contribution of VEGFR3/FLT4/CD310 inhibition to restoring a pro-inflammatory tumor myeloid compartment and suggest M-LECP cells as candidate fruquintinib targets to overcome immunosuppression in tumors." (PMID 41459512, 2025). "In this situation, the increased levels of vascular growth factors within the tumor microenvironment can promote tumorigenesis, triggered by FLT4 amplification (encoding VEGFR3) and KDR mutation (encoding VEGFR2)." (PMID 39202050, 2024). "VEGF-D is a ligand for the lymphatic growth-factor receptor VEGFR-3/Flt-4, which promotes the remodeling of blood and lymphatic vessels during growth and disease, and plays a key role in tumor metastasis." (PMID 39614360, 2024). "VEGF-C and VEGF-D stimulate angiogenesis via binding to VEGF receptor 3 (Flt-4), thereby promoting metastasis in murine tumor models including a carcinogen-induced cSCC tumor mouse model." (PMID 38847867, 2024). "Among cellular genes in both GI and skin KS lesions as compared to their respective normal tissues, both FLT4 and STC1 were increased." (PMID 37740179, 2023). "The two VEGF receptors, KDR and FLT4, are currently being explored for targeted inhibition therapy to reduce immune modulation and immunosuppression in the tumor environment." (PMID 37046832, 2023). "In summary, we detected the partial recapitulation of KS tumor microenvironment cell surface protein expression within the xenograft tissues where FLT4, KDR, UNC5A, and ADAM12 mirrored the levels detected in the human KS tumors." (PMID 37046832, 2023).
tumor (continued). "CD34, Prox-1, FLT4, and KDR are associated with endothelial cell signaling, vascularization, and angiogenesis during tumor formation." (PMID 37046832, 2023). "In a study, T4 phages were genetically engineered to express murine Flt4, known to participate in tumor lymphangiogenesis and contribute to tumor progression and metastasis." (PMID 37243023, 2023). "Other truncating mutations of tumor related genes (APC, BRCA1, EGFR, FLT4, etc) were also decreased rapidly during treatment." (PMID 36341335, 2022). "Flt4 is a transmembrane receptor involved in tumor lymphangiogenesis, with a role in tumor growth and metastasis, therefore a vaccine against this protein is expected to have a protective role against tumor progression." (PMID 33671476, 2021). "Accumulating evidence suggest that the up and downstream effectors of the VEGFC-VEFGR3/Flt4 axis form a complicated biochemical network which work in synergy to facilitate tumor lymphangiogenesis and lymphatic metastasis." (PMID 32752094, 2020). "Among them, VEGF-A and VEGF-C are expressed by the endometrium and VEGF receptor tyrosine kinases, VEGFRs 1 (Flt-1), VEGFR-2 (KDR, Flk-1), and VEGFR-3 (Flt-4), which are exclusively expressed in endothelial cells, hematopoietic stem cells, and tumor cells." (PMID 32637863, 2020). "According to our results, specific changes in the protein expression of VEGFR3/FLT4, HGFR/MET, and SLUG/SNAI2 were associated with the EMP-like phenotype of tumor cells." (PMID 32899940, 2020). "This is the case of the amplified oncogenes AKT1 and WT1, and of the receptor tyrosine kinase gene FLT4, which regulates lymphangiogenesis and tumor metastasization to lymphatic vessels." (PMID 31616467, 2019). "Studies have shown that VEGF‐C and VEGF‐D bind to its receptor VEGFR‐2 (KDR) and receptor VEGFR‐3 (Flt‐4), promoting angiogenesis and/or lymphangiogenesis, thus accelerates tumor growth and metastasis." (PMID 31478352, 2019). "VEGF-D, a ligand for the lymphatic growth-factor receptor VEGFR-3/Flt-4, induces the formation of lymphatics and promotes the spread of tumor cells to the lymph nodes." (PMID 29739412, 2018). "Our results point to a significant positive correlation between increased FLT4 expression and an aggressive tumor phenotype and resultant poor survival." (PMID 25605009, 2015). "Vascular endothelial growth factors (VEGF) -C and -D, and their corresponding receptor vascular endothelial growth factor receptor 3 (VEGFR3, also known as Flt4), are by many considered the main players in the development of tumor associated lymphatic vessels." (PMID 26305218, 2015). "From an upfront screen, we went on to demonstrate that genistein suppresses expression of matrix metalloproteinase 2 (MMP2) and of Fms-Related Tyrosine Kinase 4 (FLT4), and that it does so in cells in vitro and in tumor tissue in vivo." (PMID 25605009, 2015). "We examined immunohistochemical interactions between VEGF-C and its receptor, Flt-4 (VEGFR-3), in tumor-associated LNs." (PMID 23031500, 2012). "The VEGF-C/Flt-4 axis is therefore expressed not only by lymphatic endothelial cells but also by a variety of human tumor cells." (PMID 22952986, 2012). "Double immunofluorescent staining showed that VEGF-C in tumor cells promotes increased expression of its receptor, Flt-4, on lymphatic endothelia." (PMID 23031500, 2012). "In another type of application, T4-displayed mouse Flt4 tumor antigen elicited anti-Flt4 antibodies and broke immune tolerance to self-antigens." (PMID 21129201, 2010). "Later, however, KS tumor cells were also found to express lymphatic endothelial cell (LEC)-specific markers such as VEGF receptor-3 (VEGFR-3/flt4) and podoplanin, arguing for their lymphatic origin." (PMID 20730087, 2010). "It has been proposed that Flt-4 is restricted to be expressed on the lymphatic endothelium and tumor blood vessels." (PMID 20429915, 2010).
tumor (continued). "Among them, VEGF-C, VEGF-D, and Flt-4 were thought to be the major regulatory factors for tumor lymphangiogenesis, and likely play an important role in the lymphatic tumor metastasis." (PMID 19589137, 2009). "Recent studies have shown that Flt-4 was also expressed in many types of tumor cells and played an important role in tumor lymphatic metastasis and tumor progression by promoting tumor cell proliferation, growth, and migration." (PMID 19589137, 2009). "As the receptor for VEGF-C and VEGF-D, Flt-4 is expressed in not only the lymphatic endothelial cells, but also in the liver and spleen blood sinus, during injury repair, and in newly generated tumor blood vessel endothelium." (PMID 19589137, 2009). "Tumor cells stained strongly positive for Flt-4, and positive staining was also frequently observed in normal glandular epithelium." (PMID 17244359, 2007). "We have recently demonstrated that VEGF-C and Flt-4, which are established mediators of lymphangiogenesis, were expressed in the tumour cells of a large proportion (88% to 95%) of DCIS specimens." (PMID 17244359, 2007). "In conclusion, this study showed expression of VEGF-C and its receptor Flt-4, both representing lymphangiogenic growth factors, in intraductal tumour cells of nearly all DCIS lesions." (PMID 15841074, 2005). "Coexpression of ligand and receptor in the tumour epithelium was most frequently found for the VEGF-C/Flt-4 combination (87% of cases), followed by the combinations of VEGF-C/KDR (51%), ET-1/ETAR (37%), ET-1/ETBR (26%), and VEGF-A/KDR (25%)." (PMID 15841074, 2005). "In the majority of cases, tumour cells of DCIS showed expression of Flt-4, bFGF-R1, VEGF-C, and ETAR, whereas Flt-1 and bFGF expression was rarely observed." (PMID 15841074, 2005). "Macrophage-derived lymphatic endothelial cell progenitors (M-LECP) are a population of VEGFR3/FLT4/CD310/bone marrow-derived myeloid precursors that contribute to tumor lymphangiogenesis, metastases, and resistance to chemotherapy through activation of TLR receptors." (PMID 41459512, 2025). "It targets several receptors implicated in tumor growth and angiogenesis, including KIT, VEGFR2 (KDR), VEGFR3 (FLT4), and FLT3, making it a candidate for treating GISTs, particularly in patients who have developed resistance to standard therapies like imatinib." (PMID 40733131, 2025). "Furthermore, FLT4 increased the tumor burden of leukemic cells, as shown by their localization into the lungs, suggesting an important role of FLT4 in the regulation of leukemic cell extravasation." (PMID 40316529, 2025). "Notably, it has been demonstrated that activation of the VEGFR3/FLT4/CD310 axis in tumor macrophages can promote resistance to taxanes by inducing VEGFC expression." (PMID 41459512, 2025). "Analysis with TIMER showed strong correlation between NRP1 expression and the abundance of tumor progression-related genes, MMP1, MMP3, MMP9, VEGFC, FLT4 and CXCL12 in LUSC, while there isn’t clear association between NRP1 expression and this panel of pro-tumorigenic genes in LUAD." (PMID 34168096, 2021). "A poorly characterized but nontransforming mutation in Fms-like tyrosine kinase 4 (FLT4) was present in the tumor." (PMID 28915719, 2017). "Suppression of FLT4 is accompanied by inhibition of primary tumor neo-angiogenesis." (PMID 25605009, 2015). "Importantly, our identification of genistein-mediated suppression of FLT4 serves to provide a mechanistic explanation for its antiangiogenic action across several different tumor types." (PMID 25605009, 2015). "In this study, we analyzed genotypes of VEGF-A, KDR, Flt4, PDGFRα, HIF-1α and ERCC1 in TETs, aiming to verify whether they correlate with increased tumor risk and/or with the outcome of these patients." (PMID 26254278, 2015).
tumor (continued). "Furthermore, dissemination of tumor cells often occurs via the lymphatic system and can be blocked by interfering with FLT4 signaling." (PMID 24069224, 2013). "Tumor-associated LNs without metastasis such as SLNs and LNs contralateral to metastatic SLNs also showed increased sinuses expressing Flt-4 (data not shown)." (PMID 23031500, 2012). "In summary, our results indicated that VEGF-C, VEGF-D, and Flt-4 may promote tumor lymphangiogenesis and may provide a spreading route for tumor metastasis through a paracrine mechanism." (PMID 19589137, 2009). "Since Flt-4 is expressed in the endothelial cells of blood vessels and lymphatic vessels, VEGF-C, VEGF-D, and Flt-4 may also play important roles in tumor angiogenesis." (PMID 19589137, 2009). "Some of the Flt-4 positive lymphatic vessels contained tumor cells which were also Flt-4 positive." (PMID 19589137, 2009). "Targeting two tumour-associated antigens as a mechanism for modulating signalling within the tumour cell to elicit a therapeutic effect was validated by Zu and colleagues using a single-gene bs-diabody molecule specific for VEGFR2 (KDR) and VEGFR3 (Flt-4)." (PMID 18841159, 2008). "Moreover, an autocrine growth stimulation pattern of VEGF-C via Flt-4 has been suggested in tumours." (PMID 15841074, 2005). "In this study, VEGF-C and Flt-4, established mediators of angiogenesis and in particular of lymphangiogenesis, were expressed in the tumour cells of the majority of DCIS specimens (88 and 95%, respectively)." (PMID 15841074, 2005). "Flt-4: For Flt-4, a strong staining of tumour cells was observed in most cases (95.4%)." (PMID 15841074, 2005). "Interestingly, our results showed a sex-specific effect of FLT4 overexpression in tumor growth." (PMID 40316529, 2025). "Therefore, exploring the inhibition of the VEGFR/FLT4 pathway may offer a promising strategy for preventing tumor lymphangiogenesis and metastasis in NSCLC." (PMID 37509650, 2023). "Moreover, it has been reported that FLT4 significantly correlate with the different stages of cervical carcinogenesis; the ligand of FLT4 might effecting tumor cells directly to affect cancer development and progression." (PMID 29423105, 2018). "Thus, it would be of great interest to investigate whether E2F7/8 not only control CCBE1 and FLT4 during developmental lymphangiogenesis but also during tumor dissemination." (PMID 24069224, 2013). "The underlying mechanism may be secretion of VEGF-C and VEGF-D by tumor cells, which then function through the receptor tyrosine kinase Flt-4 in lymphatic endothelial cells in a paracrine manner and promote endothelial proliferation, differentiation and cavity formation." (PMID 19589137, 2009). "This suggested that Flt-4/Fc enhances lymphangiogenesis by affecting paracrine signaling, and that VEGF-C, VEGF-D and Flt-4 might also have an autocrine function in promoting tumor cell migration and invasion, which could eventually lead to tumor lymphatic metastasis." (PMID 19589137, 2009). "Here, we provided data showing evident VEGFR3/FLT4/CD310 expression in different subpopulations of the myeloid compartment of the tumor stroma and in the bone marrow of tumor-bearing and non-tumor-bearing mice." (PMID 41459512, 2025). "In this context, we investigated the effects of fruquintinib, a selective oral VEGFR3/FLT4/CD310 inhibitor with high affinity for VEGFR3/FLT4/CD310, on tumor growth and size on colorectal (MC38, CT26) and breast (4T1, E0771) tumors." (PMID 41459512, 2025). "VEGF receptors (KDR, FLT4, FGFR1, and FLT3) and FGF receptors support tumor angiogenesis, providing essential nutrients for growth." (PMID 39273340, 2024). "The FLT4, KDR, and UNC5A proteins were detected at high levels within the L1T2 xenografts, mirroring the human KS tumor expression patterns." (PMID 37046832, 2023).